PCAT1 (prostate cancer associated transcript 1)
Diseases named in the same sentence as PCAT1 in open-access papers (continued):
Sharing a sentence is not in itself a finding about the gene and the disease.
breast carcinoma (10 papers, 2015 to 2024). "Unsurprisingly, PCAT-1 is upregulated in breast cancer patients and is also associated with clinical parameters such as grade, tumor size, and poor clinical outcome." (PMID 37583933, 2023). "We hope that association between three lncRNAs (HULC, NPTN-IT1, and PCAT1) and breast cancer can be validated through wet experiments." (PMID 36744179, 2022). "Several studies have reported that PCAT1 can associate with breast cancer although its association with the cancer on the MNDR dataset is unobserved." (PMID 36744179, 2022). "Future studies can focus on evaluation of any association between PCAT-1 transcript levels, the certain variant of this polymorphism and breast cancer risk." (PMID 28989584, 2017). "To define the role of PCAT-1 in breast cancer pathogenesis, we then evaluated the association between its transcript levels and several clinicopathological parameters." (PMID 28989584, 2017). "LncRNA prostate cancer-associated transcript-1 (PCAT-1) is induced upon hypoxia in breast cancer cells and stabilizes HIF1α by directly interacting with the receptor of activated protein C kinase-1 (RACK1) protein and preventing RACK1-mediated degradation of HIF1α." (PMID 37583933, 2023). "PCAT1 may link to breast cancer with the ranking of three among all lncRNAs unknown to associate with breast cancer on the MNDR dataset." (PMID 36744179, 2022). "Similar in vitro studies in breast cancer cell lines are needed to identify PCAT-1 role in DSB repair in breast cancer." (PMID 28989584, 2017). "In the present study, we demonstrated significant up-regulation of PCAT-1 in a proportion of breast cancer samples compared with their paired ANCTs." (PMID 28989584, 2017). "So, in vitro functional studies are needed to explore the role of PCAT-1 in regulation of MYC expression in breast cancer tissues." (PMID 28989584, 2017). "However, in the present study, we detected PCAT-1 over-expression in about only one-quarter of breast cancer tissues compared with their paired ANCTs, which implies that it only participates in the pathogenesis of this fraction of breast tumors." (PMID 28989584, 2017). "So, PCAT-1 may contribute in the pathogenesis of breast cancer as well." (PMID 28989584, 2017). "For example, lncRNAs such as HOTAIR (breast cancer), NKILA (breast cancer metastasis), NBAT1 (neuroblastoma), MALAT1 (lung, breast, prostate and cervix cancer), MDC1-AS (bladder cancer), lncRNA-886 (esophageal and gastric cancers) and PCAT-1 (prostate cancer) have been implicated in tumorigenesis." (PMID 26087192, 2015). "The data show an upregulation of breast cancer related genes in T1 and C1 relative to 10A, including LRATD2, PCAT1, CASC19, CASC8, POU5F1B, PVT1 and MYC on chromosome 8." (PMID 38076897, 2024). "Consequently, in the present study, we evaluated the expression of PCAT-1 and its relation with MYC transcript levels in a population of Iranian breast cancer patients." (PMID 28989584, 2017). "According to our data, PCAT-1 and PCAT-14, which were decreased as a result of CCT137690 treatment in breast cancer cells, may play a role in the anti-proliferative effects of CCT137690 on breast cancer cells." (PMID 31319040, 2020). "Materials and Methods: The expression of PCAT-1 was assessed using real-time reverse transcription polymerase chain reaction in tumor samples obtained from 47newly diagnosed breast cancer patients as well as their corresponding adjacent non-cancerous tissues (ANCTs)." (PMID 28989584, 2017). "On the other hand, we could not detect any correlation between the levels of MYC and PCAT-1 transcripts in the breast cancer tissues examined." (PMID 28989584, 2017).
multiple myeloma (10 papers, 2019 to 2024). "Previous reports aimed at identification of diagnostic value of PCAT1 in human cancers reported various values ranging from 0.66 to 0.89 in diverse cancers with the best value reported in multiple myeloma." (PMID 39640681, 2024). "Long noncoding RNA PCAT1 (lnc‐PCAT1) involves in the proliferation and drug sensitivity of multiple myeloma (MM), while its prognostic role in MM patients is still obscure." (PMID 34564896, 2021). "In current study, we demonstrated that PCAT-1 was overexpressed in the patients with newly diagnosed myeloma." (PMID 31777580, 2019). "Higher expression of PCAT-1 has been observed in several cancers including colorectal, gastric, esophageal, osteosarcoma, lung, bladder, cervical, hepatocellular carcinoma, cholangiocarcinoma, and multiple myeloma." (PMID 30987615, 2019). "PCAT1, ANRIL, H19, ANGPTL1‐3, or NEAT1 upregulation induced myeloma cells insensitive to bortezomib, whereas CRNDE overexpression leads to dexamethasone tolerance." (PMID 36057947, 2023).
hepatocellular carcinoma (9 papers, 2019 to 2025). A malignant tumor that arises from hepatocytes. "In animal studies, the inhibition of PCAT-1 expression has proven effective as a tool to diminish tumor development across multiple cancer disorders including colorectal cancer, lung cancer, hepatocellular carcinoma, and squamous cell carcinoma." (PMID 40468332, 2025). "In addition, PCAT-1 was indicated to be overexpressed in hepatocellular carcinoma (HCC) patients and might serve as a novel prognostic indicator in HCC patients with poor outcomes." (PMID 31777580, 2019).
lung carcinoma (9 papers, 2017 to 2022). "The expression of long non‐coding RNA (lncRNA) prostate cancer‐associated ncRNA transcripts 1 (PCAT1) is increased in non‐small cell lung cancer (NSCLC)." (PMID 35415876, 2022). "Concurrently, the high expression of PCAT-1 is closely associated with the immunosuppression of lung cancer." (PMID 33213510, 2020). "Several studies in recent years have also found important roles of PCAT1 in lung cancer." (PMID 35415876, 2022). "A recent study found that in lung cancer tissues, the high expression of lncRNA PCAT-1 is related to the induction and infiltration of CAFs, which may be achieved via the immunosuppressive miR-182/miR-217 signaling." (PMID 33213510, 2020). "Studies have shown that lncRNA PCAT-1 expression is significantly upregulated in CRC cells and tissues, as well as in exosomes extracted from serum of lung cancer patients." (PMID 36093435, 2022).
colon cancer (8 papers, 2015 to 2025). "When rs2632159 polymorphism is present, the rs1902432 TT+TC variant genotype was shown to increase the risk of rectal cancer, and the rs785005 GG variant genotype increased the risk of colon cancer; this suggests the potential for pairwise effects of SNP–SNP interaction in the PCAT1 gene." (PMID 31253700, 2019). "However, when cases were divided into colon cancer and rectal cancer, the PCAT1 gene C-G-T-G-T haplotype decreased colon cancer risk to 0.75-fold (P=0.019)." (PMID 31253700, 2019). "When the CRC cases were divided into colon cancer and rectal cancer, we found that PCAT1 rs2632159 was associated with colon cancer risk under the dominant model (P=0.022, OR = 1.51) and with rectal cancer susceptibility under the recessive model (P=0.009, OR = 3.03)." (PMID 31253700, 2019). "In addition, PCAT1 rs1902432 polymorphism decreased colon cancer risk to 0.59-fold (P=0.030)." (PMID 31253700, 2019). "The major finding in the present study was that the PCAT1 rs2632159 SNP increased CRC susceptibility, and functioned as a risk factor for colon cancer under the dominant model and for rectal cancer under the recessive model." (PMID 31253700, 2019). "In summary, in the present study, the PCAT1 rs2632159 SNP was shown to increase CRC susceptibility, and it was shown to increase the risk of colon cancer under the dominant model and of rectal cancer under the recessive model." (PMID 31253700, 2019). "In the male subgroup, PCAT1 rs2632159 SNP also increased rectal cancer risk by 3.97-fold in the male subgroup (P=0.017), while PCAT1 rs710885 polymorphism increased CRC risk by 2.09-fold and colon cancer risk by 2.60-fold (P = 0.033, P = 0.013)." (PMID 31253700, 2019). "For example, our research found that PCAT1 rs2632159 SNP was shown to increase CRC susceptibility in a Chinese population, and the rs1902432 SNP might only have potential to be a biomarker for colon cancer risk in the Chinese population." (PMID 31253700, 2019). "The intersection of CRC vs. N and CRC vs. Ad comparisons defines lncRNAs characteristic of malignancy in colonic tumors, where significant downregulation of LINC01752 and overexpression of UCA1 and PCAT1 were found." (PMID 31694571, 2019). "Notably, TMEM220-AS1, TMEM238L, SOX6, SMAD7, TCF7L2, and PYGL were significantly downregulated in colon cancer, whereas LINC02257, PCAT1, CASC8, and POU5F1B were significantly upregulated in colon cancer." (PMID 41144378, 2025).
non-small cell lung carcinoma (8 papers, 2019 to 2025). A group of at least three distinct histological types of lung cancer, including non-small cell squamous cell carcinoma, adenocarcinoma, and large cell carcinoma. "For example, lncRNA PCAT1 reportedly suppresses the radioimmune response by regulating cGAS/STING signaling in non-small cell lung cancer." (PMID 37596700, 2023).
esophageal cancer (5 papers, 2017 to 2025). A primary or metastatic malignant neoplasm involving the esophagus. "lncRNA PCAT-1 was significantly higher in human esophageal cancer, and high PCAT-1 expression was significantly correlated with advanced clinical stage, lymph node metastasis, and poor prognosis, which is a potential prognostic factor for esophageal cancer." (PMID 28388588, 2017). "LncRNA PCAT-1 has been shown to accelerate DDP resistance and tumor growth of esophageal cancer cells." (PMID 34881242, 2021).
esophageal squamous cell carcinoma (5 papers, 2019 to 2022). Esophageal squamous cell carcinoma (ESCC) is a type of esophageal carcinoma (EC) that can affect any part of the esophagus, but is usually located in the upper or middle third. "The lncRNA prostate cancer-associated transcript 1 (PCAT1) has been reported to be involved in multiple human cancers, including oesophageal squamous cell carcinoma (ESCC)." (PMID 31273188, 2019). "In another study, enforced expression of miR-326 attenuated the promotive effect of PCAT1 on oesophageal squamous cell carcinoma (ESCC) cell growth." (PMID 35715760, 2022). "Long noncoding RNA PCAT1, present in oesophageal squamous cell carcinoma(ESCC) cell-derived exosomes, was higher in the serum of ESCC patients and may serve as a non-invasive biomarker for ESCC." (PMID 33588789, 2021).
osteosarcoma (5 papers, 2018 to 2025). A usually aggressive malignant bone-forming mesenchymal neoplasm, predominantly affecting adolescents and young adults. "In osteosarcoma, PCAT1 can promote cell proliferation, migration, invasion and other processes." (PMID 40661182, 2025).
prostate tumors (4 papers, 2014 to 2024). "The risk allele (‘T’) is associated with higher expression of PCAT1, PVT1 and c-myc in prostate tumors." (PMID 32680982, 2020). "Apart from c-myc, high levels of PCAT1 and PVT1 have been reported in prostate tumors, suggesting a common mechanism of their transcriptional dysregulation." (PMID 32680982, 2020). "Moreover, PVT1, PCAT1, and PCAT10 were significantly overexpressed in prostate tumors relative to tumor-adjacent normal tissues." (PMID 32059012, 2020).
ovarian carcinoma (3 papers, 2020 to 2022). A malignant neoplasm originating from the surface ovarian epithelium. "In ovarian cancer, miR-129-5p was significantly downregulated in OC tissues and cells, and miR-129-5p acting as tumor suppressor inhibited cell proliferation and promoted apoptosis of OC cell by attenuating the effects of PCAT-1." (PMID 32377169, 2020).
thyroid cancer (3 papers, 2023 to 2025). "This study aimed to investigate the roles of lncRNAs, specifically prostate cancer-associated transcript 1 (PCAT-1) and Fetal-lethal non-coding developmental regulatory RNA (FENDRR), in the pathogenesis of thyroid carcinoma." (PMID 40468332, 2025). "In conclusion, this study is the first to explore the gene expression analysis of lncRNAs PCAT1& FENDRR in thyroid carcinoma." (PMID 40468332, 2025). "Forty fresh thyroid cancer samples and 36 control goiter tissue samples were analyzed for gene expression levels of PCAT-1 and FENDRR via quantitative real-time polymerase chain reaction (PCR), and Associations with clinicopathological characteristics were analyzed." (PMID 40468332, 2025). "This study is the first to investigate the expression patterns of PCAT-1 and FENDRR in thyroid cancer." (PMID 40468332, 2025). "This study also aimed to evaluate PCAT-1 and FENDR as prognostic indicators for predicting the recurrence of thyroid cancer and to test their ability to discriminate between PTCs and benign thyroid tumors." (PMID 40468332, 2025). "The goal of this research was to explore the potential roles of both PCAT-1 and FENDRR lncRNAs in thyroid cancer by comparing their gene expression levels between PTC patients and control individuals." (PMID 40468332, 2025). "Although our study did not directly investigate these mechanisms, these insights suggest potential pathways through which PCAT-1 and FENDRR could exert their biological effects in thyroid cancer." (PMID 40468332, 2025). "Despite increasing interest in the importance of lncRNAs in cancer research, the precise functions of PCAT-1 and FENDRR in thyroid cancer have not yet been investigated." (PMID 40468332, 2025).
acute myeloid leukemia (2 papers, 2021 to 2022). Acute myeloid leukemia (AML) is a group of neoplasms arising from precursor cells committed to the myeloid cell-line differentiation. "As to lnc‐PCAT1 expression in the hematological malignancies, lnc‐PCAT1 is enhanced in acute myeloid leukemia patients." (PMID 34564896, 2021). "For example, lncRNAs PCA3, PCGEM1, and PCAT-1 are highly expressed in prostate cancer, and the expression level of KIAA0125 correlated negatively with the prognosis of acute myeloid leukemia (AML)." (PMID 36591508, 2022).
breast tumor (2 papers, 2016 to 2017). "In our study, we almost did not detect the expression level of the PCAT1 in either breast normal or breast tumor samples." (PMID 27897201, 2016).
cervical carcinoma (2 papers, 2022 to 2025). A carcinoma arising from either the exocervical squamous epithelium or the endocervical glandular epithelium. "Both upregulation of GOLM1 and downregulation of miR-128 can reverse the enhanced radiosensitivity effect of PCAT1 gene knockout on cervical cancer cells, thus promoting the proliferation, migration and invasion of cervical cancer cells." (PMID 35692795, 2022). "Knockdown of PCAT1 leads to upregulation of miR-128, which enhances the radiosensitivity of cervical cancer cells to proliferation, migration, and invasion." (PMID 35692795, 2022). "In vitro experiments showed that knocking down PCAT1 could improve the radiosensitivity by inhibiting the proliferation, migration and invasion of cervical cancer." (PMID 35692795, 2022).
endometrial cancer (2 papers, 2014 to 2023). Primary or metastatic malignant neoplasm involving the endometrium (mucous membrane that lines the endometrial cavity). "In addition, the high expression of PCAT1 is positively correlated with FIGO stage, myometrial invasion, lymph node metastasis, and shortened overall survival of endometrial cancer and, therefore, may be a promising biomarker for the prognosis of patients with endometrial cancer." (PMID 36757457, 2023).
glioblastoma (2 papers, 2018 to 2024). The most malignant astrocytic tumor (WHO grade IV). "The reduction of PCAT1 expression was observed in glioblastoma compared to brain cancer stem cells; consequently, dysregulated PCAT1 may be a new therapy in brain tumors." (PMID 39044190, 2024).
major depressive disorder (2 papers, 2022 to 2024). An episode of depression lasting two or more weeks without an intervening episode of mania. "NEAT1, PCAT1, RMRP, and NKILA are lncRNAs associated with neuropsychiatric phenotypes such as major depressive disorder (MDD), addictive behavior, and substance abuse." (PMID 36005827, 2022).
metastatic prostate carcinoma (2 papers, 2017 to 2021). A carcinoma that arises from the prostate gland and has spread to other anatomic sites. "For example, prostate cancer associated transcript 1 (PCAT-1) is highly upregulated in metastatic prostate cancers." (PMID 28124977, 2017). "The lncRNA PCAT1 (prostate cancer associated transcript 1) gene is localized upstream of the MYC oncogene, and was first found to be considerably over-expressed in a subset of human metastatic prostate cancer tissues." (PMID 33593347, 2021).
metastatic tumor (2 papers, 2012 to 2020). "Recent studies reveal that PCAT-1 plays a significant role in metastatic tumor progression and acquisition of chemoresistance." (PMID 32754302, 2020).
rectal cancer (2 papers, 2019 to 2022). A primary or metastatic malignant neoplasm that affects the rectum. "A more pronounced effect was observed in the male subgroup in that PCAT1 rs2632159 SNP increased rectal cancer risk by 3.97-fold (P=0.017)." (PMID 31253700, 2019). "In the subgroup analysis, the PCAT1 rs2632159 SNP also increased the risk of rectal cancer in males." (PMID 31253700, 2019). "Changes in subcutaneous tumor and liver nodule size after PCAT1 deletion were observed in a mouse model of liver metastasis from rectal cancer." (PMID 36093435, 2022).
endometriosis (1 paper, 2021). The growth of functional endometrial tissue in anatomic sites outside the uterine body. "Finally, the rs710886 SNP in PCAT1 has been associated with increased risk of developing endometriosis." (PMID 34768856, 2021). "This SNP appears to disrupt sponging by PCAT1 of miR-145, affecting the expression of FASCIN1, SOX2, MSI2, SERPINE1, and JAM-A, and the proliferative and invasive ability of endometriosis stem cells." (PMID 34768856, 2021).
gastric tumor (1 paper, 2021). "PCAT-1 increased CDDP resistance by of GC cells through miR-128 sponging that resulted in increased levels of ZEB1 expression in gastric tumor cells." (PMID 34099061, 2021). "There was PCAT-1 up regulation in CDDP-resistant gastric tumor cells." (PMID 34099061, 2021).
goiter (1 paper, 2025). Enlargement of the thyroid gland usually caused by lack of iodine in the diet, hyperthyroidism, or thyroid nodules. "For both expressions of PCAT1 and FENDRR, analysis of the area under the curve (AUC) determined that the test exhibited high accuracy in differentiation between goiter and PTC, and its use in diagnosing PTC can be supported." (PMID 40468332, 2025). "PCAT-1 expression was significantly higher in PTC (median: 3.12; IQR: 0.40–7.29) compared to goiter (median: 1.49; IQR: 0.23–3.02; p ≤ 0.001)." (PMID 40468332, 2025). "PCAT-1 and FENDRR expression levels were assessed in tissue samples from both PTC and goiter." (PMID 40468332, 2025).
herpesvirus infection (1 paper, 2019). "In detail, the up-regulated genes associated with PCAT-1 overexpression in MM cells were involved in Kaposi's sarcoma-associated herpesvirus infection, MAPK signaling pathway, TNF signaling pathway, Neurotrophin signaling pathway, etc." (PMID 31777580, 2019).
laryngeal carcinoma (1 paper, 2024). Carcinoma that arises from the laryngeal epithelium. "Xu and colleagues revealed that lncRNA PCAT1 enhances proliferation and glycolysis of laryngeal cancer cells through miR-182/PDK4 axis." (PMID 38554157, 2024).
lymph node tumors (1 paper, 2020). "In contrast, PCAT-1 levels were reduced in NAF cells and their infiltration was lower in both primary and lymph node tumors." (PMID 32754302, 2020).
prostate adenocarcinoma (1 paper, 2020). "Further, within prostate adenocarcinomas of PCAWG cohort, 17 tumors had A/A genotype, only 2 were with A/T and none were with T/T genotype but, similar to the observation in the pan-cancer data, the expression of PCAT1, PVT1, and MYC was found to be higher in those with A/T genotypes." (PMID 32680982, 2020).